CD8A (CD8 subunit alpha)
Diseases named in the same sentence as CD8A in open-access papers (continued):
Sharing a sentence is not in itself a finding about the gene and the disease.
melanoma (continued). "Of note, injection of tumor vaccine-loaded mcDC, but not of CD8α DC, elicited protective responses from subsequent tumor challenge in mice in a vaccination EL-4 thymoma model and resulted in therapeutic eradication of established EL-4 and B16 melanoma tumors." (PMID 24400008, 2013). "And the negative correlation between 6 ICD-related genes (CD8A, PRF1, IFNG, CXCR3, TNF, CD8B) and risk score and the protective function of these 6 genes in SKCM indicates that drugs targeting these genes may be a novel treatment method in melanoma." (PMID 36211436, 2022). "Together, dramatic upregulation of cytotoxic CD8α+ T cells, along with CD19+ B cells, by the pS14-WWOX7-21 peptide did not lead to melanoma growth suppression." (PMID 31752354, 2019). "Finally, the results suggested that the expression of six genes including IRF1, JAK2, CD8A, IRF8, STAT5B, and SELL had a significant ability to distinguish the responders from non-responders to anti-PD-1 therapy in melanoma with AUC > 0.6 and pAUC > 0.7." (PMID 32316408, 2020). "pS14-WWOX7-21 peptide failed to block melanoma cell metastasis and yet induced significant upregulation of the expansion of spleen helper CD4+ T cells (2-fold increase), cytotoxic CD8α+ T cells (25-fold increase) and CD19+ B cells (14-fold increase) in the germinal centers." (PMID 31752354, 2019).
viral infection (2,585 papers, 2004 to 2026). "The transcription factor BATF3 is important for the development of cDC1s, as mice lacking Batf3 expression are deficient in CD8α+ DCs and tumor-resident CD103+ DCs, making them more susceptible to CD8+ T cell-controlled viral infections and tumor growth." (PMID 33268774, 2020). "Furthermore, high-level co-expression of CD274 and CD8A is usually associated with higher tumor mutation and oncogenic viral infection." (PMID 33585244, 2020). "During viral infection, free viruses in body fluids can be neutralized by antibodies such as IgG2c, preventing further cell infection; for virus-infected cells, CD8a+ T cells exert cytotoxic effects to eliminate them." (PMID 41295528, 2025). "CD8 glycoprotein, composed of CD8α and CD8β subunits, is expressed on CD8+ cytotoxic T lymphocytes and CD8+ regulatory T cells, which are crucial for host immune responses against viral infections and cancer cells." (PMID 38020762, 2023). "Direct comparisons of the two DC subsets have been conducted in the context of viral infection due to the central role of mature CD8α+ cDC1s in cross-presentation and cross-priming of CD8+ T-cells for anti-viral responses." (PMID 35980974, 2022). "We, therefore, decided to deplete CD4 and CD8 cells in three C57BL/6J mice by using anti-mouse CD4 (Clone GK1.5) and anti-mouse CD8 (clone 2.43 against CD8a) for seven weeks following anal viral infections." (PMID 29208932, 2017). "CD8α+ conventional DCs (cDCs), a minor population among total mouse spleen DCs, have the selective ability to cross-present endogenously synthesized proteins, such as viral infection-expressed proteins and certain exogenous Ags to CD8 T cells." (PMID 27008707, 2016). "Further analyses of human CD8α-expressing PDC will delineate their role in the defense against viral infections, and—if viral vectors are used—also in anti-tumor responses." (PMID 26082771, 2015). "We and others have shown that administration of poly I:C stimulates TLR3 on CD8α+DCs enhancing cross-presentation and direct presentation to CTLs against tumors and virus infection." (PMID 24600454, 2014). "We first examined the mRNA expression levels of AsEomes, IFNγ, CD8α, and granzyme A at different time intervals following bacterial and viral infection in the spleen and head kidney." (PMID 23409078, 2013). "In mouse models, the importance of CD8α+ DCs and cross-presentation in control of virus infection is well-established." (PMID 22412374, 2012). "In support of this notion, it has previously been reported that CD8α/CD8β expression corresponds to cytotoxic lymphocyte activity in carp, allogeneic stimulation in rainbow trout, as well as virus infection in salmon." (PMID 22529969, 2012). "Mouse CD8α cDCs have been proposed to be specialized for a default tolerogenic function but to be endowed with the unique ability to cross-present antigen for the activation of naïve CD8 T cells within the context of viral infection." (PMID 18218067, 2008). "The CD8A expression profile in the high-FCR jejunum may thus indicate that its immune system is potentially more sensitive to viral infection." (PMID 34573572, 2021). "Thus, to further understand the immune response of the liver to viral infection, we analyzed the percentages of IgM+, IgD+, CD8α+ and MHC-II+ cells in the liver of control and infected animals through flow cytometry." (PMID 25338079, 2014). "However, the epigenetic regulation of CD8A in the duck and its relationship with virus infection are still unclear." (PMID 24505360, 2014). "However, the CD2+CD8α+ γδ T subpopulation was increased in all three viral infections with the greatest increase seen in PRRSV infection." (PMID 25186625, 2014). "However, the epigenetic regulation of CD8A in the duck and its relationship with virus infection remain unclear." (PMID 24505360, 2014).
viral infection (continued). "Lung cDC1s migrate to mediastinal LNs after viral infection, where they directly present antigens to naïve CD8+ T cells or transfer captured antigens to CD8α+ cDC1s, which present antigens and activate naïve CD8+ T cells." (PMID 35615351, 2022). "An important DC population that produces IL-12 under microbial stimuli conditions are CD8α+ DCs (and sometimes, CD8α− DCs) while pDCs produce both IL-12 and IFN-α in response to several virus infections." (PMID 32582186, 2020). "CD8α DC play a prominent, and sometimes exclusive, role in driving amplification of CD8+ T cells during a viral infection." (PMID 18301768, 2008). "CD103+CD11b– CD8α+ DCs take up orally administered OVA more efficiently than do other DC subsets independent of viral infection." (PMID 35993365, 2022). "Whereas, the CD3E+CD8A+CD4− clusters contributed substantially to all of top 20 TCR data in three groups’ integrated data, which indicated expanded CD8+ T cell clones contributing to immune response to viral infection." (PMID 34580278, 2021). "We recently described an alternative surrogate actiation marker approach, relying on concurrent downregulation of surface CD8α and upregulation of CD11a (α-chain of LFA-1) on effector and memory antigen-specific CD8 T cells responding to bacterial and viral-infections in mice." (PMID 20657824, 2010). "In certain viral infection models, CD8α+ dermal DCs and not LCs have the major antigen-presenting function." (PMID 17157855, 2007). "In the same way, CD8α may promote binding of FcγR to MHC class I-expressing cells coated with immune-complexes in cancer, viral infection or autoimmune disease." (PMID 17678538, 2007). "This synergizes with CD8a+ T cell activation data (higher frequency of OX40+CD137+), enabling the vaccine to not only neutralize free viruses but also more efficiently eliminate virus-infected cells, establishing a more comprehensive immune defense system against viral infection." (PMID 41295528, 2025). "During acute viral infection, absence of SPP in the eye did not affect CD4 expression but did affect CD8α and IFNγ expression in the eye." (PMID 36215312, 2022).
COVID-19 (2,120 papers, 2020 to 2026). A disease caused by infection with severe acute respiratory syndrome coronavirus 2. "A decreased abundance of a cluster of several leukocyte chemotactic factors (MCP-4, CXCL12, CCL11, CCL19, CCL25, and CCL20) was observed in the COVID-19 cases and associated with a decrease in the cytotoxic T-cell marker CD8A." (PMID 34710339, 2022). "We employed a radiolabeled minibody targeting the human CD8α subunit to interrogate the in vivo distribution of CD8 T-cells in patients admitted to the hospital with COVID-19." (PMID 38813383, 2024). "In conclusion, PET/CT imaging with a radiolabeled minibody targeting CD8α on T-cells allows the localization of CD8+ T-cell responses in vivo in COVID-19 patients." (PMID 38813383, 2024). "Surprisingly, and in contrast to CNS specimens from acute cases, post-COVID-19 brain revealed only very few parenchymal CD8a+ T cells that were numerically almost compatible to controls." (PMID 39060438, 2024). "The immunopathological changes in the spleen of patients with COVID-19 are also worthy of attention as they involve the functions of plasma cells and monocytes/macrophages and a decrease in CD8A abundance." (PMID 38455049, 2024). "Subgroup analyses of the five deceased COVID-19 patients (all males) revealed significantly upregulated proteins such as CD8A, SLAMF1 and LIF-R, HGF, CCL25, NT3 compared to the surviving patients." (PMID 37832397, 2023). "As seen with antiviral CD4+ T cells, CD8+ T cell responses (CD8+CD69+41BB+) against SARS-CoV-2 spike–containing CD8-A MP and CD8-B MP were detectable in the majority of children with convalescent COVID-19 (74% and 75% with FC > 2, respectively)." (PMID 35044955, 2022). "A recent study using artificial intelligence techniques revealed that genes involved in activation of immune pathways (IL-6, TNF, JAK2, IL-1B, SERPINE1, TGFB1, CD8A, and VWF) serve as major hubs in the COVID-19- thrombocytopenia interactomes." (PMID 35372456, 2022). "Additionally, a smaller number of biopsies (COVID-19 n = 5, controls n = 6) were analyzed for the expression of ACE2 and TMPRSS2 as mediators of virus entry as well as for the expression of EpCAM, CD8α, CD31, and CD163." (PMID 34420043, 2021). "Though both unexposed and COVID-19 patients responded consistently to CMV and PHA, they did not respond to CD8-A and CD8-B MPs substantially." (PMID 36248882, 2022).
breast cancer (1,898 papers, 2003 to 2026). A primary or metastatic malignant neoplasm involving the breast. "The CD8A gene (encoding for CD8) was associated with an improved outcome in several public breast cancer datasets." (PMID 29559701, 2018). "Significance of this analysis is exemplified by the fact that mutations of BTLA, CD28, CD4, and CD8A genes in the GO term cell surface receptor-linked signal transduction contribute to sporadic breast cancer risk." (PMID 27911271, 2017). "We demonstrate that high HMOX1 and low CD8A expression in breast cancer is associated with poorer outcomes, suggesting that these patients may benefit from HO inhibition to overcome immunosuppression in the TME." (PMID 40627458, 2025). "The present study reports DVL2 association with CD8α levels in HER2+ breast cancer biopsy tissues." (PMID 36809986, 2023). "Higher CD8A expression has been associated with a better prognosis in breast cancer patients." (PMID 31715586, 2019). "To assess the clinical relevance in breast cancer, we examined the association between type I IFN signaling, CD8+ T cell infiltration (via CD8A), and HO-1 (HMOX1) expression." (PMID 40627458, 2025). "Global HGFL loss in the PyMTHGFL−/− mouse model also led to an increase in CD8a T cells, F4/80+ and iNOS+ macrophages, and decreased Arginase-1 macrophages in mammary tumors." (PMID 40282397, 2025). "Recent studies have shown that CD32/CD8a/CD28/CD3ζ chimeric receptor cells directly kill breast cancer cells, suggesting the existence of cell surface myeloid FcγR alternative ligands (ALs)." (PMID 39962623, 2025). "Further, the mammary tumors from MMTV-RONΔMyeloid mice compared with controls show increased numbers of CD8a+ T cells and CD4+ T cells." (PMID 40282397, 2025). "For example, 16 weeks of RT-HIIT reduced IL-6 and soluble CD8a levels in chemotherapy-treated breast cancer patients, improving systemic and physical fatigue by 32.0% and 31.2%, respectively." (PMID 40699773, 2025). "As expected, murine mammary carcinoma 4T1 grew more quickly in mice treated with anti-CD8α antibody than in mice treated with IgG isotype control." (PMID 37014700, 2023). "PLA2G2A was also positively correlated with the CD45 antigen PTPRC, B-cell marker CD79A, and CD8 T cell marker CD8A in breast cancer patients." (PMID 36357424, 2022). "Further, MMTV-RONΔMyeloid mammary tumors compared with controls show increased numbers of CD8a+ T cells and CD4+ T cells." (PMID 35626096, 2022). "In this cohort of over 600 tumor–normal pairs and an independent validation cohort (TCGA), both GSAct and CD8A expression metrics show modest—but consistent—correlation between breast cancer and tumor-adjacent normal breast tissue." (PMID 36376974, 2022). "Bioinformatic analysis of human breast cancer samples confirmed an association between DDR1 expression level and CD8A expression or CD8 T cell signatures in human patients." (PMID 35027528, 2022). "Importantly, these results were validated in the GEO dataset, where elevated CD8a/FOXP3 was predictive of improved survival in ER– breast cancer patients." (PMID 40663402, 2025). "Overall, in the tumor microenvironment examined via immunohistochemistry and immunophenotyping, mammary tumors from PyMT TKΔEpithelial mice showed a significant increase in the percent of macrophages, NK cells, and CD8a positive cells present compared to PyMT RONF/F tumors." (PMID 40282397, 2025). "We found that SLAMF6 expression was highly correlated not only with the expression of T-cell markers (CD3E, CD8B, CD8A, and CD4) but also with upregulation of TCF7, PDCD1 encoding PD-1, GZMK, and effector-associated genes including IFNG and PRF1 in breast cancer." (PMID 38287061, 2024). "Further subgroup analyses revealed a significant negative correlation between baseline TIL score and age (p < 0.05) as well as baseline CD8α levels and N-stage> 1 (p < 0.05) denoting possible association between DVL2 and immune-regulatory markers of HER2+ breast cancer." (PMID 36809986, 2023).
breast cancer (continued). "Additionally, CD8α levels were negatively correlated with NLR (rho = − 0.59; p = 0.030) denoting probable crosstalk between DVL2 and CD8α proteins in predicting prognostic outcomes of HER2+ breast cancer." (PMID 36809986, 2023). "To further validate our in vitro analyses of DVL2 role in HER2+ breast cancer, we performed TIL-scoring and mapped DVL2 and CD8α protein levels via immune staining in a preliminary sample of 24 HER2+ breast cancer patients at baseline biopsy (N = 24) and post NAC resection (N = 14) tissues." (PMID 36809986, 2023). "Therefore, CD3 and CD8a expression in the PFOA + ZAL group at D50—the group that we focused on—were analyzed by IHC as part of a cross Breast Cancer and the Environment Research Program (BCERP) consortia endpoint." (PMID 35163327, 2022). "In a compendium of four human breast cancer datasets, we show a clear association between high LDH-A and HIF-1α gene expression and poor outcome, and an inverse pattern of disease-free survival with immune-related gene expression (CD3E/CD4 and CD8A)." (PMID 30248111, 2018). "Using a combination of these markers, 60 HR+/HER2+ breast cancer patients were classified into the following subtypes: (a) IHC-III: CD8A+; (b) IHC-IV: CD8A− and KRT5+; (c) IHC-II: CD8A−, KRT5− and GFRA1+; (d) IHC-I: CD8A−, KRT5−, GFRA1− and PFKP+." (PMID 40133264, 2025). "NAC is frequently used for early and advanced stage breast cancer patients, and our study demonstrates that high DVL2 is found in biopsy tissue before the NAC and high CD8α levels are found in biopsy tissues post NAC." (PMID 36809986, 2023). "Furthermore, in patients with breast cancer, a limited bioinformatics analysis shows that patient outcome (metastases-free survival) is associated with an inverse pattern of metabolism-related (LDH-A and HIF-1α) and immune-associated (CD3E and CD8A, CD4) gene expression." (PMID 30248111, 2018). "In return, they demonstrated a positive correlation between the CD8α, CD8β and IFN-γ expressionb and the efficacy of doxorubicin treatment in patients with breast cancer." (PMID 22949815, 2012). "Additionally, the TCGA dataset was used to correlate expression levels of CD8A (a marker indicative of CD8+ T cells) and VCAN across subtypes of breast cancer." (PMID 40361362, 2025). "For luminal breast cancers, we found that high WWOX/HIF1A ratios demonstrate a more robust anti-tumour immune response, as evidenced by increased expression of CD8A and FOXP3, which are instrumental in recruiting cytotoxic T-cells and suppressing pro-tumourigenic inflammation." (PMID 41007296, 2025). "Additionally, the functional MRI parameters and IHC results in patients with breast cancer after NACT also showed a close correlation between D value and CD8a (r = 0.631, P = 0.028)." (PMID 35646652, 2022). "Of note, the strongest correlation of ERβ with CD8A and GZMB was observed in breast cancer." (PMID 33462142, 2021). "Functional experiments showed that A2M-AS1 enhances breast cancer cell proliferation, invasion, and migration, and bioinformatics analysis showed that A2M-AS1 potentially regulates cell adhesion molecule pathway members, including CD2, CD8A, and SELL." (PMID 32352014, 2020). "In our study, CD8A protein levels were increased in non-treated ER+ DMBA mammary tumors in the HFD offspring." (PMID 32580156, 2020). "Protein levels of the T effector cell marker CD8a, assessed by IHC, were not different in mammary tumors between TAM and TAM + JEKHT-treated rats." (PMID 30640711, 2019). "Moreover, high levels of IL12A mRNA in human breast cancer samples correlates with expression of DC-related transcription factors and GRZMB, CD8A, and IFNγ expression, suggesting an active anti-tumor T cell response." (PMID 26500653, 2015).
breast cancer (continued). "To determine the impact of irradiation on the tumor immune infiltrate in Brca1co/coMMTV-Cre mammary tumors, we isolated single cell suspensions from tumor tissues and conducted flow cytometry analysis of CD45+ leukocytes stained for CD11b, Gr 1, F4/80, CD4, CD8α, and PD-1." (PMID 41208884, 2025). "Similarly, DVL2 positively correlates with NLR, while a negative correlation was found between DVL2 and CD8α, and in between CD8α and post NAC TIL score, suggesting an association between DVL2 and TIL score in HER2+ breast cancer." (PMID 36809986, 2023). "Therefore, we have determined the expression of CD8α and IFN-γ in canine mammary tumors." (PMID 32225066, 2020). "Consequently, CD8+ T-cell effector (Teff) score, comprising gene expression of IFNG, PRF1, CD8A and CD8B, and BATF3-DC score, calculated with the expression level of BATF3, IRF8, THBD, CLEC9A, and XCR118 were markedly increased in the high SLAMF6 group than in the low SL AMF6 group in breast cancer." (PMID 38287061, 2024). "Conversely, in the lung cancer and breast cancer cohorts, SIN3B did not exhibit any correlation with CXCL9/10/11 or CD8A." (PMID 39316363, 2024).